ADM (adrenomedullin)
Diseases named in the same sentence as ADM in open-access papers (continued):
Sharing a sentence is not in itself a finding about the gene and the disease.
Obesity (20 papers, 2011 to 2025). Accumulation of substantial excess body fat. "Regarding metabolic regulation, hyperglycemia, obesity, and dyslipidemia are associated with ADM levels." (PMID 34990470, 2022). "The increase in ADM levels found in the case of low-grade inflammation in VAT associated with obesity may be a counter-regulatory (compensatory) mechanism for inflammatory cytokines." (PMID 32503285, 2020). "Recent studies on key players associated with obesity and diabetes such as adipocytokines, gut microbiota, adrenomedullin, hyaluronan, vanin and matrix metalloproteinase have deciphered unknown linkage present across PC as well as PCDM." (PMID 30567565, 2018). "Under overnutrition condition, inhibition of hepatic ENTPD5 will trigger the excessive expression and secretion of ADM to inhibit BAT thermogenesis, causing obesity and metabolic dysfunctions." (PMID 40788055, 2025). "Studies on adipokines and other biomarkers of obesity have become important in obesity research, and ADM was also defined as a new member of the adipokine family." (PMID 36010070, 2022). "In obesity, ADM expression is upregulated in adipocytes and circulating ADM concentrations are increased." (PMID 35681200, 2022). "In a previous PEA‐proteomics study, ADM and FABP4 were positively associated with BMI‐defined obesity." (PMID 34151535, 2021). "Previous reports indicate that ADM expression significantly increased obesity compared to the control group." (PMID 32503285, 2020). "In other words, obesity may partly stem from the dysregulation of eATP metabolism and ADM secretion in hepatocytes." (PMID 40788055, 2025). "ADM and ADM receptors are highly expressed in vascular tissues, and plasma ADM level is markedly increased in people with obesity indicating that it may be critically involved in the pathogenesis of OH." (PMID 36835355, 2023). "It has been reported that there is an increased plasma ADM level in people with obesity, and ADM might derive from many other organs or tissues, such as WAT." (PMID 35745637, 2022). "People with obesity display an obvious increase in ADM levels in plasma." (PMID 35745637, 2022). "Factors that upregulate ADM production in obesity are incompletely understood." (PMID 35681200, 2022). "Even though the long-term significance of the ADM alteration observed in the present study is unknown, the relationship between tobacco exposure and elevated blood pressure, type 2 diabetes, and obesity has been previously demonstrated." (PMID 25623364, 2015). "Moreover, the ADM has been found to be related to chronic diseases such as obesity and comorbidities such as diabetes, atherosclerosis and coronary heart disease, all of which have been associated with in utero tobacco exposure." (PMID 25623364, 2015). "Furthermore, plasma concentration of the antiadipogenic factor ADM increases with obesity, the incidence of type 2 diabetes, cardiovascular diseases and inflammation." (PMID 22039494, 2011). "A panel of hypoxia-regulated genes (VEGF, ADM, LDHA, SLC2A1) showed consistently higher mean values in the endometrium of women with obesity and in uteri of mice with increased weight vs normal controls, although statistical significance was not reached." (PMID 33836495, 2021). "This evidence correlates with previous studies in mice in which obesity was shown to be correlated with the presence in adipose tissue of macrophages that induce ADM and CGRP mRNA, suggesting an increased role of inflammation in human obesity due precisely to increased expression of these peptides." (PMID 38891025, 2024).
diabetes (19 papers, 2013 to 2025). "The association between rs182052 and ADM levels was more significant in subjects with diabetes mellitus (β = 0.344, P = 0.001 after adjusting for age and sex)." (PMID 23936408, 2013). "Such experimental evidence may implicate ADM as a fundamental factor in maintaining insulin homeostasis and normoglycemia, and dysregulation of ADM maybe one of the causal factors in diabetes." (PMID 35324977, 2022). "An alternative hypothesis suggests that increased ADM in diabetes is a late effect associated with progressing vascular endothelial dysfunction." (PMID 24347823, 2013). "Several molecules, including adrenomedullin, adipokines (including lipocalin, leptin, and adiponectin), and calprotectin, have been reported to be associated with PDAC‐associated diabetes mellitus." (PMID 40351037, 2025). "GCF adrenomedullin concentrations were significantly increased in individuals with chronic periodontitis and diabetes mellitus." (PMID 37342498, 2023). "In our study, statin use was nominally associated with three surrogate marker components (plasma proteins) of GrimAge: ADM, cystatin C, and TIMP-1, all of which are associated with diabetes." (PMID 34083497, 2021). "Our study, however, does not exclude a local increase in the level of ADM, for example, in eye tissues, before its rise in the serum; in patients with diabetes >10 years' duration, the level of ADM is already higher." (PMID 24347823, 2013). "To clarify the role of adrenomedullin in diabetic nephropathy, we induced diabetes using STZ in AMKO mice." (PMID 23957015, 2013). "The fact is that the level of ADM in diabetes undergoes changes even in the pediatric population and that their direction and significance require further investigations." (PMID 24347823, 2013). "It has been shown that the production of adrenomedullin is increased in the vasculature in patients with diabetes and that the local action of adrenomedullin in the kidneys is upregulated in the early phase of diabetic nephropathy." (PMID 23957015, 2013). "ADM and adiponectin are both hormones with well-recognized roles in the cardiovascular disease and diabetes." (PMID 23936408, 2013). "In contrast, oxidative stress can induce adrenomedullin production, and it is possible that adrenomedullin increases in patients with diabetes to counterbalance increased oxidative stress." (PMID 23957015, 2013). "Impaired β cell function, along with the impact of PDAC-released factors (e.g., adrenomedullin (ADM), IGF-1, and macrophage inhibitory factor (MIF) on pancreatic islets, may contribute to the induction of diabetes associated with PDAC." (PMID 39596226, 2024). "Our previous studies have demonstrated that both circulating ADM and ADM expression in OMAT were increased in GDM patients, indicating that ADM may be involved in the pathogenesis of insulin resistance in GDM as observed in diabetes." (PMID 35390031, 2022). "Therefore, we hypothesize that endogenous adrenomedullin in diabetes may act to protect against the development of diabetic nephropathy." (PMID 23957015, 2013). "The changes observed in the levels of ADM, IL-17, and VEGF support their possible involvement in the microvascular complications of diabetes." (PMID 24347823, 2013). "Although the role of ADM in diabetes has not been well established, elevated plasma ADM levels were observed in diabetic patients." (PMID 23936408, 2013).
endothelial dysfunction (18 papers, 2010 to 2025). In vascular diseases, endothelial dysfunction is a systemic pathological state of the endothelium (the inner lining of blood vessels) and can be broadly defined as an imbalance between vasodilating and vasoconstricting substances produced by (or acting on) the endothelium. "For instance, oxidized low-density lipoprotein (ox-LDL) has been implicated in the induction of endothelial dysfunction and ferroptosis through the modulation of ADM transcription and the activation of the AMPK signaling cascade." (PMID 38812011, 2024). "Mid-regional pro-adrenomedullin (MR-proADM), a stable precursor fragment of adrenomedullin, reflects endothelial dysfunction and vascular integrity—both of which are severely compromised in sepsis." (PMID 40724799, 2025). "Elevated levels of ADM correlate with an increase in endothelial dysfunction, which leads to excessive fluid leakage into the alveolar spaces, resulting in pulmonary edema and ARDS." (PMID 39594987, 2024). "Existing studies had confirmed that biomarkers of endothelial dysfunction, such as the microalbuminuria to creatinine ratio and adrenomedullin, can serve as indicators for predicting the prognosis of septic patients." (PMID 39364026, 2024). "Evidence suggests that adrecizumab increases ADM plasma levels by shifting ADM from the interstitium to the blood, thereby reducing vascular smooth muscle cell vasodilation and endothelial dysfunction." (PMID 37317092, 2023). "Since the virus-induced endothelial dysfunction is a possible contributing factor to the evolution of COVID-19 infection, the need to evaluate the role of Adrenomedullin (ADM) has been recently highlighted." (PMID 33556140, 2021). "For example, ADM is a vasoactive peptide synthesized by endothelial and vascular smooth muscle cells, which is increased by endothelial dysfunction and volume overload." (PMID 34869664, 2021). "Levels were highest in fatal cases, suggesting that adrenomedullin may serve as a useful biomarker for predicting disease severity and endothelial dysfunction in dengue." (PMID 41013386, 2025). "Adrenomedullin was targeted for its role in endothelial dysfunction and vascular tone regulation, with studies cross-referenced to evaluate its predictive value for acute respiratory distress syndrome (ARDS), septic cardiomyopathy, acute kidney injury (AKI), hepatic dysfunction, and coagulopathy." (PMID 39594987, 2024). "Moreover, abnormalities in ADM expression play a central role in the development of endothelial dysfunction and in the different steps of atherogenesis." (PMID 31906326, 2020). "In this study, we provide evidence that the endothelial phenotype of cortactin-deficient mice is caused by increased actomyosin contractility as a consequence of decreased ADM secretion leading to endothelial dysfunction as manifested by increased permeability." (PMID 27357373, 2016).
myocardial infarction (16 papers, 2010 to 2025). Gross necrosis of the myocardium, as a result of interruption of the blood supply to the area, as in coronary thrombosis. "In patients with acute myocardial infarction, high ADM levels have been associated with impaired left ventricular function and death." (PMID 28050899, 2017). "Increased ADM levels in patients with hypertension, heart failure (HF), and myocardial infarction (MI) have been linked to increased PKA activation." (PMID 27713345, 2010). "Confirming this, a proteomic approach allowed, among a panel of 175 different markers, the identification of six markers, including adrenomedullin, able to predict long-term outcomes in patients with renal failure and myocardial infarction." (PMID 39200990, 2024). "They observed that the plasma ADM concentration was elevated during the early stages of acute myocardial infarction, with the magnitude of elevation directly corresponding to the clinical severity of the condition." (PMID 38069140, 2023). "In contrast to another potential biomarker, atrial natriuretic peptide (ANP), ADM demonstrated a distinct profile of myocardial effects, suggesting its potential as a valuable therapeutic intervention in the post-myocardial infarction setting." (PMID 38069140, 2023). "The proADM and ADM increased expressions in infarcted cardiac tissue led to increased plasma MR-proADM levels in circulation following acute myocardial infarction." (PMID 35888580, 2022). "In experimental study of myocardial infarction in mice models, the gene expression and protein level of proADM and ADM were augmented." (PMID 35888580, 2022). "Plasma ADM level increased in the early phase of acute myocardial infarction proportionally to its clinical severity and it was further elevated in patients with congestive heart failure." (PMID 33540505, 2021). "In analogy, MSCs transplantation has been shown to limit fibrosis of myocardial infarction and dilated cardiomyopathy, which has been attributed to adrenomedullin, regarded as an antifibrotic factor secreted by MSCs." (PMID 22432015, 2012). "In mouse models of myocardial infarction, treatment with adrenomedullin or a recombinant form of VEGFC that selectively activates VEGFR3 has led to the resolution of disease-induced edema and inflammatory factors, successfully averting cardiac fibrosis and dysfunction." (PMID 41221452, 2025). "Moreover, one study found elevated serum levels of ADM in patients with acute myocardial infarction (AMI)." (PMID 35355972, 2022). "Interestingly, ADM is upregulated in instances of congestive heart failure and myocardial infarction, as a compensatory mechanism to protect the vasculature." (PMID 34362171, 2021). "Of the 4 hub genes, ADM was upregulated in CAD (GSE56885), PPFIA4 and TPBG were upregulated in patients with ischemic heart disease (GSE48166), and FAM162A was downregulated in patients with myocardial infarction (GSE141512)." (PMID 37637145, 2023). "Although mid regional pro-adrenomedullin (MR-pro ADM) has no biological activity, it has been attracting attention as a biomarker for the prognosis of heart failure, myocardial infarction, community-acquired pneumonia, septic shock, and COVID-19." (PMID 34440272, 2021).
Hyperglycemia (12 papers, 2013 to 2024). An increased concentration of glucose in the blood. "Recent studies show that ADM and its receptors are expressed in rat adipose tissue, administration of ADM induces hyperglycemia, which can be reversed by an ADM neutralizing antibody." (PMID 35390031, 2022). "To determine the impact of hyperglycemia on ADM and its receptors in adipose tissue, we treated the human adipocytes with increasing doses of glucose." (PMID 35390031, 2022). "Our results showed that glucose dose-dependently increased mRNA expressions of ADM and its receptor components CRLR, RAMP2 and RAMP3 suggesting the association between hyperglycemia and elevated ADM in diabetic patients." (PMID 35390031, 2022). "To determine the impact of hyperglycemia on ADM and its receptors in β-cells, we treated NIT-1 cells with increasing doses of glucose for 24 hours." (PMID 35324977, 2022). "The plasma concentration of adrenomedullin also increased in the diabetic patients, and hyperglycemia increases the production of adrenomedullin in the vasculature." (PMID 23957015, 2013). "Indeed, studies have worked to find that adrenomedullin and exosomes derived from PDAC cause paraneoplastic dysfunction of human beta-cells and suppress insulin secretion thereby causing hyperglycemia." (PMID 39200119, 2024). "Additionally, PDAC-associated systemic inflammation and tumor-derived factors, such as adrenomedullin and islet amyloid polypeptide, can induce insulin resistance, further contributing to hyperglycemia." (PMID 39405289, 2024). "Hyperglycemia itself in GDM may be one of the stimulants for the elevated ADM and its receptor expressions in adipocytes, thus contributing to the disturbed lipid metabolism by enhancing ADM’s action." (PMID 35390031, 2022). "Taking into account the negative correlation between ADM and HbA1c in the ≤10 years' subgroup, this is presumably caused by the protein consumption in unfavorable conditions of hyperglycemia." (PMID 24347823, 2013). "However, it is considered that PDAC may lead to DM through releasing cancer cell mediators stimulating hyperglycaemia or β-cell dysfunction and enhancing insulin resistance, such as adrenomedullin, islet amyloid polypeptide." (PMID 38067280, 2023). "Correlations with measures of hyperglycemia, adiposity, lipids, blood pressure and inflammation were generally weaker, exceptions being FABP4 and ADM which correlated with body fat content (r = 0.75 and r = 0.69, respectively), and IL6 which correlated with CRP (r = 0.63) and WBC (r = 0.62)." (PMID 33279861, 2021).
ovarian carcinoma (12 papers, 2012 to 2025). A malignant neoplasm originating from the surface ovarian epithelium. "At the molecular level, metabolic reprogramming has also been implicated in treatment resistance, with adrenomedullin shown to induce cisplatin chemoresistance in ovarian cancer through glucose metabolism remodeling." (PMID 41169363, 2025). "ADM was known to promote angiogenesis, cell survival, and metastasis, and was associated with poor prognosis in ovarian cancer patients." (PMID 31146747, 2019). "In studies of ovarian cancer, the suppression of ADM gene expression has been shown to significantly inhibit cell proliferation and enhance chemosensitivity." (PMID 40565016, 2025). "In a separate epithelial ovarian cancer investigation, ADM was found to promote cancer cell migration through the activation of the integrin α5/β1 signaling pathway." (PMID 40565016, 2025). "Expression of adrenomedullin (ADM) in ovarian cancer tissues is related to resistance to platinum-based drugs." (PMID 37408575, 2023). "This study was aimed to investigate the role of ADM on angiogenesis in epithelial ovarian cancer (EOC) and its possible mechanism." (PMID 28091613, 2017). "It was reported that HIF-1α induced the expression of ADM mRNA under normoxic and hypoxia conditions in the human ovarian carcinoma cell line OVCAR-310, which was opposite to what we observed." (PMID 28091613, 2017). "Silencing of the ADM gene in HO8910 cells (ovarian carcinoma cell line) can decrease Bcl-2 and phospho-ERK (p-ERK) expression, which inhibits cell proliferation." (PMID 27556517, 2016). "This study was aimed to examine the function of adrenomedullin (ADM) in macrophage polarization and their further effects on the migration of ovarian cancer cells." (PMID 23434647, 2013). "ADM expression was observed in various kinds of tumors, including breast, lung, colon and ovarian cancer." (PMID 23434647, 2013). "Conversely, a recent study reported that silencing of the ADM gene in HO8910 ovarian cancer cells was accompanied by growth inhibition and chemosensitization through downregulation of ERK and bcl-2 expression." (PMID 22859951, 2012). "In this study we investigated the role of ADM as a growth factor for ovarian cancer cells and as a modulator of macrophages." (PMID 22859951, 2012). "In conclusion, ADM could polarize macrophages similar to TAMs, and then polarized macrophages promote the migration of ovarian cancer cells via activation of RhoA signaling pathway in vitro." (PMID 23434647, 2013). "Since ovarian cancer is a chemosensitive disease in most patients we can speculate that the tissue concentration of chemotherapeutics is increased when levels of ADM are elevated, leading to better control of the disease and a longer disease-free interval." (PMID 22859951, 2012). "In addition, adrenomedullin also could induce cisplatin resistance in ovarian cancer through reprogramming of glucose metabolism." (PMID 40547013, 2025). "Since ovarian cancer is a disease that spreads in an environment rich in macrophages, which are believed to be the main source of ADM production, in this study we investigated the role of ADM as a growth factor for cancer cells and as a modulating factor in macrophages." (PMID 22859951, 2012). "Therefore, use of an ADM antagonist would be inappropriate in managing ovarian cancer patients." (PMID 22859951, 2012). "In the investigation of epithelial ovarian cancer (EOC), there is evidence demonstrating that ADM functions as an upstream regulatory molecule of VEGF and HIF-1α, thereby facilitating tumor angiogenesis through the upregulation of VEGF and HIF-1α expression." (PMID 40565016, 2025). "Elevated ADM levels have recently been observed in a variety of cancers, including RCC, prostate cancer, non-small cell lung carcinoma, and ovarian carcinoma." (PMID 27556517, 2016).